TNF (tumor necrosis factor)
Diseases named in the same sentence as TNF in open-access papers (continued):
Sharing a sentence is not in itself a finding about the gene and the disease.
Obesity (continued). "Previous studies have suggested that TNF-α and IL-6 are involved in obesity-related insulin resistance and atherosclerosis." (PMID 26714835, 2015). "The pre-acupuncture results showed significant difference between the three grades of obesity and the controls regarding TNFα, IL-6 and hsCRP." (PMID 27275202, 2015). "In summary, we identified that inflammatory response is a possible mechanism that can explain the relationship between obesity and asthma, and control of the inflammatory response through the TNF-α pathway is a means for treating obesity-related asthma." (PMID 25658739, 2015). "Previous studies suggest there is low-grade inflammation in obesity along with altered levels of several circulating factors, such as increases in the plasma levels of TNF-α, CRP, IL-6, and other biological markers of inflammation." (PMID 26699936, 2015). "In obese rodent models and humans with NAFLD or obesity, a strong inverse correlation has been observed between serum TNFα levels and insulin-stimulated glucose metabolism." (PMID 26077338, 2015). "We also assessed the development of obesity-induced inflammation by measuring hippocampal level of TNF-alpha, and the extent of protein oxidation by titrating nitro-tyrosine (N-Tyr)." (PMID 26696835, 2015). "The effect of obesity, of causing chronic low-grade inflammation with an elevation of inflammatory markers (such as CRP, TNF-α, and IL-6) that increase the risk of cardiovascular disease, is even more pronounced in PCOS." (PMID 26124830, 2015). "Subsequently, the novel function of TNF-α is verified in different rodent obesity models as well as in obese humans." (PMID 26339623, 2015). "As a first approach, we assessed the effects of TNF-α on the expression of a panel of miRNAs previously related to heart disease, obesity, type 2 diabetes and inflammation." (PMID 26112171, 2015). "Our data are corroborated, in part, by the previous findings showing elevated TNF-α levels in obesity and macrophage recruitment and angiogenesis in breast adipose tissue." (PMID 26200663, 2015). "As calcium mobilization and calcium-sensing receptor (CaSR)-induced secretion of cytokines like TNF-α is increased in T cells from inflammatory disease such as sepsis, we propose that these pathways link obesity and inflammation to the development of PE." (PMID 26569331, 2015). "Obesity is characterised by low-grade inflammation, reflected, in part, by increased expression of circulating (TNF-α) and local (TNF-α, IL-1β) proinflammatory cytokines in diet-induced obese mice." (PMID 26618193, 2015). "Both TNFα protein and mRNA are robustly upregulated in obesity, an increase that has been shown to correlate with the development of insulin resistance." (PMID 26217222, 2015). "In order to investigate the role of a broad range of pro- and anti-inflammatory cytokines in obesity, serum levels of TNF-α, IFN-γ, IL-2, IL-4, IL-5, IL-10, IL-12, IL-13, and GM-CSF were compared between obese and non-obese participants." (PMID 25781614, 2015). "Generally, expansion of adipose tissue in obesity leads to increased macrophage infiltration and inflammation with enhanced production of proinflammatory cytokines such as tumor necrosis factor α (TNF-α) and interleukin 6 (IL-6)." (PMID 25816341, 2015). "Tumor necrosis factor-alpha has been shown to be over-expressed in white adipose tissue in various animal models of obesity." (PMID 25938677, 2015). "Treating obesity by exercise or through dietary means also reduced pulmonary TNF-α levels and AHR in the DIO-OVA mice." (PMID 25658739, 2015). "Still, TNFα was the first adipokine suggested to represent a link between obesity, inflammation and diabetes." (PMID 26578976, 2015). "Here, it was reported that adipose-derived tumour necrosis factor alpha (TNF-α) levels in mice were increased during the advancement of obesity, but when TNF-α was neutralised, insulin sensitivity was improved." (PMID 26257839, 2015).
Obesity (continued). "The Axl transgenic mice exhibited phenotypes of obesity and type 2 diabetes, such as hyperglycemia, hyperinsulinemia, and insulin resistance, and showed elevated plasma TNF-α level." (PMID 25954309, 2015). "The adipokine TNF-α is an important mediator of inflammation seen in obesity in both the periphery and hypothalamus." (PMID 26580647, 2015). "In obesity, the expanding adipose tissue releases a large numbers of mediators, including TNF-α, IL-6, and MCP-1 as well as FFA, which can interfere with insulin signaling." (PMID 25816341, 2015). "Based on these results, we conclude that exercise mitigates HFD- induced cardiomyopathy by decreasing obesity, inducing IL-10, and reducing TNF-α in mice." (PMID 25954207, 2015). "Particularly warranted are investigations into which factors stimulate TNF-α-producing alveolar macrophages in the obesity-related asthma and which mechanisms are involved in the relationship between treatments of obesity and improved asthmatic lesions." (PMID 25658739, 2015). "Realizing that obesity is a chronic inflammatory state, we also explored the baseline and post-intervention levels of cytokines such as TNF-alpha, IL-6, IL-10, and PAI-1." (PMID 26611872, 2015). "Plasma sCD163 is regarded as a marker of macrophage activity and a long-circulating marker of TNFα, and concentrations of sCD163 are increased in obesity and T2DM." (PMID 25624106, 2015). "In this study, we identified that pre-existing obesity exacerbates subsequent asthmatic lesions via alveolar macrophages and their TNF-α production." (PMID 25658739, 2015). "Previous models of diet-induced and genetic obesity has shown that adipose tissue presents an important source of pro-inflammatory adipocytokines, such as tumor necrosis factor α (TNF-α), interleukin-1 (IL-1), and interleukin-6 (IL-6) during weight gain." (PMID 26247966, 2015). "Although it was initially suggested that the main source of TNFα in obesity were adipocytes, it is now well recognized that M1 macrophages infiltrated in adipose tissue are responsible for increased levels of this cytokine." (PMID 26578976, 2015). "While concentrations of TNF-α and IL-1β appeared to be elevated in certain subgroups of patients, the role of confounding factors, such as age and obesity, should be taken into account when planning future research on these immune markers." (PMID 26065825, 2015). "Obesity and IR can lead to elevated levels of pro-inflammatory cytokines (e.g., TNF-α, IL-6, IL-1b, etc.) in both the peripheral and central nervous system of humans (T2DM:) and animals." (PMID 26340637, 2015). "TNF-α can also exacerbate asthma and play a crucial role in the relationship between obesity and asthma." (PMID 25658739, 2015). "There are two types of evidence indicating obesity as a chronic inflammatory illness: the release of proinflammatory cytokines such as TNFα, IL-6 and IL-1β from adipose tissues and infiltration of macrophages into the WAT." (PMID 26347815, 2015). "In most cases, adipose tissue (AT) is an important site of obesity-induced IR, and it can also affect the liver and muscle by releasing cytokines, including adipokines such as TNF-α." (PMID 26136779, 2015). "The second explanation is that the production of adipokines by fat tissue, such as IL-6 and tumor necrosis factor-α, enhances obesity-induced inflammation." (PMID 25889813, 2015). "Increases in tumor necrosis factor- α (TNF- α) and serum leptin levels with aging have been associated with obesity and atherosclerosis." (PMID 26473487, 2015). "White adipose tissue (WAT) is an important site for obesity-related chronic inflammation where adipose tissue macrophages (ATMs) produce proinflammatory cytokines and chemokines, such as tumor necrosis factor alpha (TNFα) and MCP-1." (PMID 26308623, 2015). "Comparison between obesity and control groups regarding routine laboratory tests and levels of inflammatory mediators (TNF-α, IL-6, hsCRP) pre acupuncture (mean ± SD)." (PMID 27275202, 2015).
Obesity (continued). "In the present study, obesity induced an increase in the serum concentrations of TNF-α, IL-6 and IL-1β in the ob/ob group." (PMID 26714835, 2015). "It is known that during processes such as obesity or atherosclerosis, there are increased levels of proinflammatory cytokines such as IL-6 and TNF-α, which are capable to activate NF-κB in different tissues." (PMID 26055507, 2015). "Type 2 diabetes, hypertension, dyslipidemia and increased values of waist circumference, body fat, leptin, fibrinogen, IL-1β, hsCRP and TNFα were related to obesity (p < 0.05)." (PMID 25897330, 2015). "Obesity, specifically abdominal or visceral obesity, leads to high levels of pro-inflammatory adipokines including IL–6, IL–1β, leptin and TNF-alpha." (PMID 26437377, 2015). "It is well known that the increased IL6 and TNFα circulating levels in obese patients have led to the conclusion that obesity is characterized by a subjacent chronic low-grade inflammation." (PMID 26694359, 2015). "Obesity is often considered a systemic inflammatory condition with increased levels of inflammatory cytokines, including tumor necrosis factor-alpha and interleukin-6." (PMID 25890172, 2015). "TNF-α is an inflammatory cytokine that plays an important role in insulin resistance observed in obesity and chronic inflammation." (PMID 25623542, 2015). "We also reported that, in lean animals, EWAT exposed to IH became pathological, behaving like excess fat in obesity, as it exhibited increases in macrophage recruitment and secretion of IL-6 and TNF-α." (PMID 25873766, 2015). "Adipocyte-derived factors such as TNF-α are significantly increased in obesity and are good predictors of the development of type 2 diabetes." (PMID 25629558, 2015). "Obesity induces the activation of proinflammatory signaling in ATMs, resulting in upregulation of pro-inflammatory cytokines (i.e., TNF-α, IL-6 and inducible nitric oxide synthase (iNOS)), which act locally, contributing to IR14." (PMID 26459940, 2015). "Comparison between obesity groups post acupuncture as regards routine lab analysis and inflammatory mediators (TNF-α, IL-6, hsCRP) (mean ± SD)." (PMID 27275202, 2015). "Plasma and adipose tissue levels of inflammatory cytokines such as IL-6 and TNF-α have been reported to increase along with the progression of obesity." (PMID 25954309, 2015). "For instance, expression of TNF-α, which is a common pro-inflammation cytokine, is upregulated in the pancreatic islets of patients and animal models with obesity." (PMID 25984739, 2015). "This recognition begins with the observation that adipocyte is a significant source of endogenous tumor necrosis factorα (TNF-α) at which secretion is substantially stimulated by obesity." (PMID 26339623, 2015). "In total, 50 obese patients undergoing bariatric surgery were included, and paired samples of visceral adipose tissue (VAT) and subcutaneous adipose tissue (SAT) were examined for gene expression of obesity markers leptin, adiponectin and TNFα and PPARγ." (PMID 24427296, 2014). "Several reports have shown increased TNF-α, IL-6, resistin and leptin expression in obesity, type 2 diabetes, cardiovascular disease and metabolic syndrome." (PMID 24481132, 2014). "The first molecular link between inflammation and obesity, TNF-alpha, was identified when this inflammatory cytokine was discovered to be over-expressed in adipose tissues of rodent models of obesity." (PMID 24991532, 2014). "At first, scientists proposed that TNF-α was implicated in the pathogenesis of cachexia, yet it became apparent that TNF-α was positively correlated with obesity with expression in adipocytes." (PMID 25309775, 2014). "TNF-α and IL-6 are the cytokines that are known to be expressed during inflammatory condition and are elevated in obesity-related inflammatory diseases." (PMID 25006525, 2014). "Our data demonstrate that low testosterone and obesity independently increased cerebrocortical mRNA levels of both TNFα and IL-1β." (PMID 25224590, 2014).
Obesity (continued). "Multiple inflammatory cytokines (TNF-α, IL-6, etc.)and signaling pathways (JNK, NF-κB) have been implicated in obesity-induced insulin resistance." (PMID 25333972, 2014). "In this study, gene expression values of the obesity marker genes leptin, adiponectin, TNFα and PPARγ were measured in paired SAT and VAT samples of 50 obese patients." (PMID 24427296, 2014). "The inflammatory process in obesity also involves other important cytokines, including classic ones such as TNF-α and IL-6, chemokines such as MCP-1 and MIP-1α, and proteins involved in vascular homeostasis such as the inhibitor plasminogen 1 (PAI-1)." (PMID 25324698, 2014). "Partially resulting from the increased infiltration of macrophages, the expression of TNFα is also elevated in adipose tissue in obesity." (PMID 24817881, 2014). "Because obesity is associated with insulin resistance and an increased risk of GDM, we also examined the effect of obesity on plasma TNF-α level." (PMID 25202741, 2014). "Obesity leads to a dramatically changed secretory profile of adipose tissue, characterized by increased production of proinflammatory cytokines, such as TNF-α, IL-1β and IL-6." (PMID 24516630, 2014). "The purpose of this study was to examine the role of phospholipase D1 (PLD1) in leptin-induced expression of the proinflammatory cytokine, tumor necrosis factor (TNF)-α, and to suggest a molecular link between obesity and respiratory tract inflammation." (PMID 25047119, 2014). "Targeting inflammation in the hypothalamus by the inactivation of IκB kinase or TNFα blockade protects against defective thermogenesis, obesity and IR, suggesting that hypothalamic dysfunction may precede and mechanistically contribute to obesity-associated IR and Type II diabetes (Type II DM)." (PMID 25358444, 2014). "Obesity leads to an increase in TNF-α expression in WAT, which ultimately leads to adipocyte dysfunction." (PMID 24416415, 2014). "Tumor necrosis factor (TNF-α) is an inflammatory cytokine implicated in metabolic disorders, including obesity and IR." (PMID 25551102, 2014). "The aim of this study mainly focused on the effect of TNFα on the development of adiposity in genetic obesity-prone young mice." (PMID 24522555, 2014). "TNF-α, which is increased in obesity, induces MK expression in adipocytes, and is therefore a potential candidate for the upregulation of MK." (PMID 24516630, 2014). "Several studies have shown an important role of adipose tissue macrophages in inflammation in obesity through the production and release of proinflammatory mediators such as IL-1, TNF-α, IL-6, and CCL2." (PMID 24398136, 2014). "On the other way, the adipocyte-derived plasma protein adiponectin has been shown to be decreased by obesity and to inhibit TNF-α-induced expression of endothelial adhesion molecules." (PMID 24816278, 2014). "Expression of TNF-α is increased in obesity and insulin resistance in humans and is positively correlated with insulin resistance." (PMID 24733068, 2014). "In conclusion, in the absence of T and B cells, the NK cells are also able to produce IFN-γ and TNF-α, which are relevant to macrophage recruitment in the adipose tissue during obesity." (PMID 24823865, 2014). "From being considered the mediator of cachexia to a pivotal regulator of obesity and insulin resistance, the role of TNF-α has diversified since its identification in adipose tissue in 1993." (PMID 25309775, 2014). "As per the current literature, there was a significant elevation in HF‐induced TNFα expression, a cytokine known to be increased in response to obesity and indeed during pregnancy complications." (PMID 25096554, 2014). "Correlation between leptin and resistin and the inflammatory markers was found to be highly dependent on obesity, in contrast to the one between adiponectin and TNF-α." (PMID 24736687, 2014).
Obesity (continued). "Obesity-related cytokines, such as IL-6, TNF-α, as well as adiponectin, visfatin, and leptin play important roles in the development of NAFLD, causing ROS-mediated hepatocellular injury." (PMID 25548896, 2014). "Obesity increases the size and activity of adipocytes, leading to release of inflammatory molecules (e.g., IL-17, IL-22, TNF-α, IL-6, and monocyte chemoattractant protein 1 (MCP-1), tissue necrosis and subsequent accumulation of activated macrophages." (PMID 25548896, 2014). "The representative inflammatory cytokines, TNF-α and IL-6, were increased under the obesity condition." (PMID 24879081, 2014). "ZAG was downregulated by TNFα and other proinflammatory cytokines in obesity, suggesting that its pattern is similar to that of adiponectin." (PMID 24899788, 2014). "In contrast, a correlative relationship was demonstrated between biomarkers of inflammation in the blood (i.e., TNF-α and IL-1) and obesity and IR in horses, as well as laminitis." (PMID 24977043, 2014). "Another theory for explaining the increased amounts of IL-6 in obesity and insulin resistance states is that elevated levels of IL-6 are a secondary defense response to higher amounts of TNF-α." (PMID 24563869, 2014). "Obesity is underpinned by a chronic state of inflammation resulting from the increase in expression of inflammatory mediators such as TNF-α and IL-6." (PMID 25309775, 2014). "The first functional link between obesity and inflammation was found in obese mice where adipose tissue was observed to secrete TNF-α." (PMID 25477778, 2014). "TNF-α is considered to be a possible therapeutic target because it was up-regulated in multiple rodent-obesity models and TNF-α blunted insulin signaling in insulin targeting tissues." (PMID 25077824, 2014). "Alongside being associated with the development of obesity and insulin resistance, TNF-α is central to the chronic inflammatory state present in obesity." (PMID 25309775, 2014). "To investigate these relationships and their potential interactions, we first examined the effects of experimentally-induced low testosterone and obesity on brain levels of two established pro-inflammatory markers, TNFα and IL-1β." (PMID 25224590, 2014). "In other words, TNF-α, as an important pathophysiological culprit in obesity, stimulates IL-6 release." (PMID 24563869, 2014). "Studies of anti-inflammatory cytokine tumor necrosis factor α (TNF-α) demonstrated its relationships with obesity and insulin resistance." (PMID 25601838, 2014). "Obesity increased TNFα mRNA levels (P<0.05) in VAT as well as the plasma TBARS (P<0.001) and protein carbonyls (P<0.001) in septic patients." (PMID 25244356, 2014). "In VAT, TNFα mRNA levels were statistically significantly higher in the sepsis & obesity group compared with the sepsis group (P<0.05)." (PMID 25244356, 2014). "A main source of ROS is the increased exposure of target tissue to inflammatory cytokines such as IL-1, TNF, and IL-6 which are increased in obesity." (PMID 25140176, 2014). "It is well established that obesity is associated with activation of JNK stress kinase and enhanced inflammatory response as monitored by the endogenous levels of IL-6, TNF-α, RANTES and CCR5 receptor in the adipose tissue." (PMID 24986468, 2014). "In summary, our evidences of obesity promotion in TNFα deficient obese mice proposed that TNFα might correlate with other signaling pathways in obese development, although the relative role of TNFα in adipogenic network such as chemerin/CMKLR signaling still remained evaluated." (PMID 24522555, 2014). "Hereinto, as a part of the inflammatory cascade, TNFα is a chief and pleiotropic cytokine involved in the regulation of cell proliferation, differentiation, lipid metabolism, and obesity." (PMID 24522555, 2014). "Then, the following concerns are raised: (i) Does elevated TNFα in obese subjects play as a secondary response to obesity?" (PMID 24522555, 2014).